DENND11 (DENN domain containing 11)
Description:
Probable guanine nucleotide exchange factor (GEF). May promote the exchange of GDP to GTP, converting inactive GDP-bound small GTPases into their active GTP-bound form (Probable). May play a role in neuritogenesis, as well as in neuronal recovery and/or restructuring in the hippocampus following transient cerebral ischemia (By similarity).
Synonyms: KIAA1147; LCHN; PRO2561
Tractability: PROTAC: ubiquitination databases record sites on it.
Gene: Protein-coding gene on chromosome 7 (141,656,728 to 141,702,166, reverse strand). Ensembl gene ENSG00000257093.
Subcellular location (Human Protein Atlas): Golgi apparatus
Gene Ontology:
Cellular component: cytoplasm
Genetic constraint (gnomAD): Loss-of-function variants: 31 observed, 39.9 expected, observed/expected ratio (o/e) 0.78, 90% interval 0.58 to 1.05. The upper end of that interval is the gene's LOEUF score, 1.05, which puts it in group 4 of 6, group 1 being the genes least tolerant of losing a copy. Missense variants: 449 observed, 532.26 expected, observed/expected ratio (o/e) 0.84, 90% interval 0.78 to 0.91. Synonymous variants: 233 observed, 212 expected, observed/expected ratio (o/e) 1.1, 90% interval 0.99 to 1.23.
Homologues: Orthologues: chimpanzee DENND11 (100% identical), rat Dennd11 (96% identical), mouse Dennd11 (96% identical), pig DENND11 (96% identical), dog DENND11 (95% identical), macaque DENND11 (87% identical), guinea pig DENND11 (86% identical), rabbit DENND11 (75% identical), tropical clawed frog dennd11 (74% identical), zebrafish dennd11 (72% identical).